MUC5B (mucin 5B, oligomeric mucus/gel-forming)
Diseases named in the same sentence as MUC5B in open-access papers (continued):
Sharing a sentence is not in itself a finding about the gene and the disease.
COVID-19 (continued). "Therefore, we examined if MUC5B rs35705950 is associated with severe COVID-19." (PMID 34888316, 2021). "After excluding the MUC5B locus, the effect for COVID-19 hospitalisation was larger in all and <60-year-old patients when using whole-genome PRSs compared with sentinels PRS results." (PMID 40247961, 2025). "The viral-induced MUC5Bpos secretory cells, in addition to expressing MUC5B that is involved in COVID-19 pathology, also expressed genes indicative of viral and proinflammatory signatures." (PMID 40980495, 2025). "These include the most strongly associated IPF risk variant in genome-wide association studies (GWAS), located at the promoter of MUC5B, which displays an opposite direction of effect in IPF and COVID-19 (i.e. the IPF risk allele was protective for COVID-19)." (PMID 40247961, 2025). "A few studies have reported significant upregulation of several mucin genes, including the gel-forming mucins such as MUC5AC and MUC5B by the bronchiolar epithelial cells of COVID-19 patients." (PMID 38999930, 2024). "Shared genetic signals between IPF and severe COVID-19 were identified near MUC5B, DPP9 and ATP11A, although the signals at MUC5B and ATP11A had opposite effects on the risk for the two diseases." (PMID 37410458, 2023). "Located in the enhancer region of the MUC5B, rs35705950, is a known risk factor for IPF, and a high mortality rate was observed among the COVID-19 patients with pre-existing IPF." (PMID 35482673, 2022). "In the airway epithelium of an explant lung of a severe ICU admitted COVID-19 patient, dramatically reduced MUC5B protein and mRNA expression was found when compared with control lung." (PMID 34888316, 2021). "Evidence suggests that the considerable elevation of IL-6 cytokines in severe COVID-19 patients is linked to massive mucus production by stimulating the expression of the two predominant mucin genes (MUC5AC and MUC5B) in tracheobronchial epithelial cells." (PMID 34046036, 2021). "The MUC5B risk allele had a different effect compared with other IPF predisposing alleles and protected against COVID-19 hospitalization in the elderly." (PMID 34888316, 2021). "Hypersecretion of mucus in the bronchioles and air sacs of the patients with COVID-19 blocks the small airway, which is related to the uncontrolled MUC5B defense mechanism and the abnormal secretion of MUC5A." (PMID 33381519, 2020). "This could be explained by the different direction of effect that the MUC5B variant has for IPF and COVID-19." (PMID 40247961, 2025). "Interestingly, a Mendelian randomisation analysis based on 15 genome-wide significant IPF risk variants known at the time revealed that, when the MUC5B locus was excluded, IPF had a causal effect on COVID-19 severity." (PMID 40247961, 2025). "The role of MUC5B in mitigating severe COVID-19 is an emerging area of interest." (PMID 40543387, 2025). "In COVID-19 patients who also had type 2 diabetes, our results indicated that patients carrying the minor variants of LZTFL1 and RAVER1 (and probably also IFNAR2 and MUC5B) are more likely to have hospitalization-requiring COVID-19 than the general population." (PMID 39752416, 2025). "Regarding the genetic polymorphisms, a higher allele frequency of the LZTFL1 and IFNAR2 minor variants significantly correlated with greater COVID-19 disease susceptibility (hospitalization) and severity, and a similar tendency was observed for the RAVER1 and the MUC5B variants." (PMID 39752416, 2025). "Furthermore, another study described the abundant presence of mucin, especially MUC5B, in the distal airway regions of patients with COVID-19, beyond the reach of bronchoscopy, making the intervention challenging." (PMID 39337895, 2024). "Although the COVID Host Genomics Initiative (throughout a GWAS meta-analysis) revealed some SNP's (in genes SFTPD, MUC5B, SLC22A31, and ACE2) involved in the susceptibility/or protection against severe COVID-19, the complete human genomic landscape of COVID-19 is incomplete." (PMID 38524554, 2024).
COVID-19 (continued). "Another GWAS study in Thai suggested a protective effect of IL17B on 5q32 against disease, and a recent release from IHG showed that MUC5B and ELF5 on chr11 might be associated with immune system regulation in the lungs in the development of COVID-19." (PMID 36649279, 2023). "Further study found MUC5B playing a protective role against COVID-19." (PMID 35292003, 2022). "The latest reports showed abnormal MUC5B expression in COVID-19 patients." (PMID 35292003, 2022). "MUC5B rs35705950 genotype in white subjects with severe COVID-19 and controls." (PMID 34888316, 2021). "Materials and Methods: Clinical exome data of 103 individuals was analyzed to identify sequence variants in five selected candidate genes: ACE2, TMPRSS2, CD209, IFITM3, and MUC5B to assess their prevalence and role to understand the COVID-19 infectivity and progression in our population." (PMID 33101356, 2020). "The composition of sputum in samples from patients with asthma, chronic obstructive pulmonary disease, cystic fibrosis, COVID-19, and other respiratory diseases share similarities, containing double-stranded RNA, mucins (mainly MUC1, MUC5AC, and MUC5B), cell debris, and lipids." (PMID 39337895, 2024). "In COVID-19, we found decreased, although statistically nonsignificant, MUC5B in airway epithelial cells, which includes goblet cells, consistent with our genetic associations having opposite effects in these two diseases." (PMID 39040187, 2024). "In large airway tissues, genes related to the mucosal layer (MUC4, MUC5AC, MUC5B) as well as cytokine-mediated signaling pathway genes (CCL20, CXCL1, CXCL6, CXCL6, MMP1) and type I interferon genes (IFIT3, ISG15, STAT1, MX1) were upregulated in COVID-19." (PMID 35233546, 2022). "We did not observe significant differences in MUC5B or DPP9 expression in lungs from patients who died of COVID-19 when compared with control lungs, which could be due to the limited number of samples in the study we examined (GEO: GSE159585)." (PMID 39876559, 2025). "We did not observe significant differences in MUC5B or DPP9 expression in lungs from patients who succumbed to COVID-19 when compared to control lungs, which could be due to the limited number of samples in the study we examined (GSE159585)." (PMID 39040187, 2024).
chronic obstructive pulmonary disease (25 papers, 2011 to 2025). A chronic and progressive lung disorder characterized by the loss of elasticity of the bronchial tree and the air sacs, destruction of the air sacs wall, thickening of the bronchial wall, and mucous accumulation in the bronchial tree. "MUC5B is implicated in several pulmonary diseases, including chronic obstructive pulmonary disease (COPD), asthma, cystic fibrosis, and severe community-acquired pneumonia (CAP)." (PMID 39768847, 2024). "As an example, in the literature some results have indicated that one of MUC5B variants predominate in mucus associated with chronic obstructive pulmonary disease (COPD) and cystic fibrosis." (PMID 29315346, 2018). "We identified elevations in airway mucin 5AC (MUC5AC) and MUC5B concentrations during spontaneous and experimentally induced chronic obstructive pulmonary disease (COPD) exacerbations." (PMID 35239513, 2022). "Some studies have reported that MUC5B is one of the primary mucins in the sputum of patients with chronic obstructive pulmonary disease (COPD)." (PMID 36304160, 2022). "Previous studies showed that MUC5B participates in the development of pulmonary diseases, such as pulmonary fibrosis, chronic obstructive pulmonary disease (COPD) and bronchiectasis." (PMID 35292003, 2022). "In the respiratory system, GLP‐1RA has been shown to regulate Muc5b expression in airway epithelial cells, and this effect has been hypothesised to benefit patients with chronic obstructive pulmonary disease and cystic fibrosis." (PMID 41146523, 2025). "For instance, studies by Thornton and co-workers have established that in respiratory mucin networks, its oligomeric mucin composition (MUC5AC, MUC5B) shows variation between diseased (e.g., cystic fibrosis, chronic obstructive pulmonary disease (COPD)) and healthy subjects." (PMID 30979166, 2016). "Plantier and colleagues demonstrated by immunohistochemistry that, in contrast to chronic obstructive pulmonary disease, MUC5B was the predominant mucin detected in the abnormal mucus cells observed in the honeycombing areas of the fibrotic lung in patients with IPF." (PMID 23940607, 2013). "Different subtypes of mucin have differing properties and predominate in different disease states (MUC5AC dominates in asthma; MUC5B dominates in chronic obstructive pulmonary disease (COPD)." (PMID 35399263, 2022). "In diseases such as CF and chronic obstructive pulmonary disease (COPD), MUC5B is found to be predominant, whereas in healthy patients, MUC5AC is the main mucin." (PMID 33396283, 2020). "IL-1β is also elevated in lungs of patients with MUC5B hypersecretion respiratory disease, such as chronic obstructive pulmonary disease (COPD) and cystic fibrosis." (PMID 31309122, 2019). "We have previously shown that IL-17A or Th2 cytokines also enhanced mucin (MUC) 5AC and MUC5B induction in NHBE cells, which causes the over production of mucus in chronic airway disorders such as chronic obstructive pulmonary disease (COPD) and asthma." (PMID 26418032, 2015). "In human pathological conditions, such as asthma, chronic obstructive pulmonary disease (COPD) and cystic fibrosis, mucin expression is altered with an increase in the amounts of both MUC5B and MUC5AC." (PMID 21602926, 2011). "MUC5B is essential for cilia motility, while MUC5AC is more responsive to environmental or infectious factors, and elevated concentrations of MUC5AC may contribute to the development of chronic obstructive pulmonary disease (COPD)." (PMID 37894512, 2023).
lung carcinoma (25 papers, 2015 to 2026). "Bioinformatic analysis revealed that high expression of MFGM (logrank p = 3.2 × 10−7), ANGL4 (logrank p = 0.0022), and MUC5B (logrank p = 0.00041) was associated with poor overall survival in lung cancer patients, whereas elevated GCN1 levels (logrank p = 0.012) correlated with better survival." (PMID 41011152, 2025). "Moreover, it seems that MUC16, MUC21 and MUC5B showed high mutation rates, mRNA expression and close relations to tumor immune infiltration may be still a great target for lung cancer target and immune therapy." (PMID 32807223, 2020). "Conversely, Several studies hint at a potential link between MUC5B expression and specific pathological subsets or stages of lung cancer, though definitive conclusions await further validation." (PMID 40655139, 2025). "Another study also showed that a high MUC5B expression is prognostic for poor survival in lung cancer patients, particularly those with IMA." (PMID 40655139, 2025). "FOXA3 and SPDEF induce MUC5AC and MUC5B, while HNF4A induces MUC3 in human lung cancer cells harboring a KRAS mutation." (PMID 36860703, 2022). "In this study, the effects of integrin β1 subunit on MUC5AC and MUC5B production were examined in NCI–H292 human lung cancer epithelial cells." (PMID 34504957, 2021). "On the other hand, MUC5B has been observed to exhibit a contrasting role in lung cancer." (PMID 40655139, 2025). "A study based on the proteomic profiling of plasma exosomes from lung cancer patients with metastasis suggested that MUC5B could serve as a potential biomarker for diagnosing lung cancer brain metastasis." (PMID 41011152, 2025). "Notably, the MUC5B enhancer region in lung cancer cells exhibits chromatin accessibility, with RNA polymerase II loading near the key SNP rs35705950—indicating a direct role for this variant in enhancer function." (PMID 40655139, 2025). "Studies indicate that while MUC5B serves a protective role in healthy epithelial tissues, its aberrant secretion in lung cancer may promote aggressive cancer behavior, particularly in lung adenocarcinomas (LUAD)." (PMID 40655139, 2025). "By applying different data analysis strategies to proteomic data, researchers found that 11 proteins in both saliva and serum exosomes were highly potent candidates for lung cancer diagnosis, among which A1AG1, AQP5, and MUC5B were highlighted due to their association with cancer." (PMID 35158999, 2022). "Moreover, certain mutation sites of the MUC5B gene are significantly correlated with the response and survival rate of NSCLC patients after radiotherapy, which will offer valuable implications for the individualized treatment of lung cancer." (PMID 40655139, 2025). "However, it is unknown whether SPDEF directly binds to the loci of MUC5AC and/or MUC5B in lung carcinoma cells." (PMID 28255028, 2017). "The crude hazard ratio (HR) of the MUC5B high expression group (score ≥ 9) compared to the MUC5B low expression group (score < 9) was 2.658 (95% CI, 1.260–5.608; P = 0.0102), which indicated that MUC5B-high expression status increased the hazard of lung cancer-related death." (PMID 25733373, 2015). "One study identified twelve proteins, such as members of the annexin family (annexin A1, A2, A3, A5, A6, A11), along with PR-OM1, MUC1, BPIFA1, CRNN, MUC5B and IQGAP, which showed significant differences between lung cancer patients and healthy individuals." (PMID 40575159, 2025). "Proteins such as BPIFA, MUC5B, CRNN, and IQGAP warrant further investigation for their potential role in lung cancer screening." (PMID 41573685, 2025). "MUC5B, IQGAP, ENO1, and SPARCL1 were identified in salivary exosomes of lung cancer patients from a comparative proteomics analysis and confirmed via a Western blot analysis." (PMID 35158999, 2022).
lung carcinoma (continued). "Compared with normal tissues, the expression of ADM2, CLIC6, KIF20A, LAD1, MUC5B, and TNS4 was up-regulated, and the expression of ATG16L2, KCNK3, MAFF, NKD1, and SPATA13 was down-regulated in lung cancer tissues." (PMID 34804921, 2021). "Furthermore, a comparative proteomics analysis revealed that MUC5B, IQGAP, ENO1 and SPARCL1 were identified in the salivary exosomes of lung cancer patients." (PMID 40575159, 2025). "Although a few studies have focused on MUC5B in lung cancers, no report has detailed the relationships between MUC5B expression and clinicopathological features in NSCLC." (PMID 25733373, 2015). "In addition, the circSULF2 is up-regulated in lung cancer tissues in comparison with adjacent normal lung tissues, and in lung cancer cell lines when compared to normal lung cell lines, and its expression is positively correlated with MUC5B (r = 0.266, P = 0.001) but not MUC5AC." (PMID 37324942, 2023). "In lung carcinoma, the MUC5B gene was illustrated to be upregulated by the long non-coding RNA MUC5B-AS1, promoting lung cancer cell mobility in vitro and metastasis in vivo, which was associated with poor outcomes in patients with lung carcinoma." (PMID 32695780, 2020). "When lung cancer subjects were compared with normal subjects, the protein expression levels of MUC5B and IQGAP in salivary exosome samples were significantly higher in the lung cancer group; however, none of the four protein expression levels in saliva samples showed a significant difference." (PMID 35158999, 2022).
lung disease (25 papers, 2016 to 2025). "This implies that MUC5B promotor variant is associated to fibrosing lung disease despite large differences in allele frequencies across different ethnical populations." (PMID 41091209, 2025). "In mouse models, abnormal expression of genes specifically expressed in the respiratory system, such as surfactant protein C (SFTPC) deficiency and mucin 5B (MUC5B) overexpression, can also cause spontaneous lung diseases similar to clinical phenotypes." (PMID 38405059, 2024). "Genetic background and epigenetic modifications have been identified as important factors in fibrotic lung diseases, among which the MUC5B promoter polymorphism is a common gene variant." (PMID 37554509, 2023). "Identifying the associated influencing factors of the MUC5B gene in pulmonary diseases will contribute to the exploration of explicit signaling pathways in MUC5B overproduction." (PMID 31309122, 2019). "Our findings strengthen the hypothesis that MUC5AC and MUC5B are yet another contributing factor to smoking-associated lung disease progression." (PMID 39769414, 2024). "Mucin encoded by MUC5B (chr11, p15.5 –lead SNP: rs35705950) is an important component of the innate immune response, and the presence of its promoter polymorphism, rs35705950, has a positive effect on the outcome of lung diseases through increased expression of MUC5B." (PMID 39752416, 2025). "Additionally, a borderline significant association was found in males between MUC5AC and MUC5B, which highly colocalizes with a MUC5B eQTL in lung tissue, and several studies have linked this variant to pulmonary disease like idiopathic pulmonary fibrosis and COVID-1926,27." (PMID 40021682, 2025). "Considering that an increase in mucous‐secreting cells is a common feature of several lung diseases, we also evaluated the production of the two main mucins in the lung: Muc5ac and Muc5b." (PMID 34170075, 2021). "MUC5B is overproduced in the airspaces of patients with mucoinflammatory lung diseases including COPD51." (PMID 34853335, 2021). "Collectively, these results suggest that MUC5AC and MUC5B might be involved in COPD pathogenesis or may be biomarkers of lung disease." (PMID 39769414, 2024). "It is identified in a child with severe lung disease and homozygous MUC5B:p.Glu5621*." (PMID 33526882, 2021). "The allele frequency of MUC5B was similar to the reported allele frequencies in other European populations, but unlike many other studies MUC5B was not statistically significant associated with lung disease, although there was a numerical association." (PMID 41091209, 2025). "MUC5B disproportion could also be found in other pulmonary diseases." (PMID 35292003, 2022). "MUC5B disproportion could also be detected in other pulmonary diseases and smoke exposure." (PMID 35292003, 2022). "Another notable result was the presence in the list of various mucin-encoding genes (MUC5B, MUC12, and MUC16), which are commonly observed mutated in many cancers and have been previously linked to colorectal, ovarian and hepatological cancers, as well as to severe fibrotic lung disorders." (PMID 31156702, 2019). "MUC5B and MUC5AC are the most common gel forming mucins in the airways of human CF and CF-like lung disease mouse model." (PMID 40496925, 2025). "Increased EGFR signaling, TGF-α production, and mucins (MUC5AC and MUC5B) expression have been reported in the airways of CF patients; however, the causative role of EGFR in CF-like lung disease has not been demonstrated, thus warranting further investigation." (PMID 40406132, 2025).
lung disease (continued). "Previous studies in adult mice with conditional deletion of Nedd4-2 identified epithelial remodeling of the distal airways with increased numbers of mucin-producing goblet cells, expression of Muc5b and impaired mucociliary clearance as key features of IPF-like lung disease in this model." (PMID 34200296, 2021).